CD5 (CD5 molecule)
Diseases named in the same sentence as CD5 in open-access papers (continued):
Sharing a sentence is not in itself a finding about the gene and the disease.
B-cell lymphoma (continued). "Usually, a combination of morphological, immunophenotypic and molecular findings allows for a precise sub-classification of CD5-positive, low-grade B-cell lymphomas of the spleen." (PMID 34898558, 2021). "BLV infection has three stages: the silent aleukemic stage; the persistent lymphocytosis (PL) stage, which is characterized by the polyclonal expansion of non-neoplastic CD5+ B-lymphocytes; and the EBL stage, as manifested by malignant CD5+ B-cell lymphoma." (PMID 33804456, 2021). "Flow cytology of his cerebral spinal fluid demonstrated a lambda light chain-restricted population of B-cells consistent with a CD5+ CD10+ B-cell lymphoma." (PMID 30228918, 2018). "This study provides information about the occurrence of T-cell markers other than CD5 in B-cell lymphomas, their frequent histological subtypes, and their prognostic significance in DLBCL." (PMID 28380441, 2017). "Light chain restriction by FCM was observed in 26/27 B-cell lymphomas positive for T-cell markers other than CD5." (PMID 28380441, 2017). "We here report the failure of rFVIIa to control DAH in a patient with CD5+ B-cell non-Hodgkin's lymphoma and cryoglobulinemic vasculitis." (PMID 25114814, 2014). "MCL is a subtype of B-cell lymphoma, derived from CD5-positive antigen-naïve pregerminal center B-cells within the mantle zone that surrounds normal germinal center follicles." (PMID 23590763, 2013). "CD5 is also occasionally expressed on B-cell neoplasms, but its clinicopathological significance in low-grade B-cell non-Hodgkin's lymphomas (NHL), notably MALT lymphomas, remains obscure." (PMID 21892966, 2011). "Furthermore, CD5 has different clinicopathologic features in different B-cell lymphomas and with different prognosis." (PMID 40973845, 2025). "Categorization of B-cell NHL relies on expression of CD5 and CD10 for basic classification." (PMID 40075660, 2025). "However, specific immunohistochemical markers for B-cell lymphoma, including CD5, CD10, CD23, BCL6, CyclinD-1, and CD38, which are typically negative." (PMID 39834941, 2024). "It is very unusual for a low-grade B-cell lymphoma (BCL) to co-express CD5 and CD10." (PMID 38535060, 2024). "MALT lymphoma is a CD5−/CD10− B-cell lymphoma with co-expression of bcl-2 in B-cells." (PMID 37958219, 2023). "Intravascular large B-cell lymphoma, another rare subtype of aggressive B-cell lymphoma, may also uncommonly express CD5." (PMID 34898558, 2021). "Excepting CD5, this study has not addressed the underlying biological mechanisms that drive clinical behaviour in aggressive B‐cell lymphoma, and genetic investigations and cell‐of‐origin immunostainings were not conducted universally." (PMID 35845206, 2021). "But CD10 and CD5 were infrequently expressed in patients with HBsAg-positive B-cell NHL." (PMID 31120924, 2019). "In contrast to CD5, the significance of other T-cell markers rarely expressed in B-cell lymphomas remains unclear." (PMID 28380441, 2017). "Finally, very rare instances of CD5/CD10-double positive B cell lymphomas have been reported." (PMID 34898578, 2021). "It was found that B-cell lymphomas were highly labeled with CD20, CD45, PAX-5, whereas T-cell lymphomas were heavily labeled with CD3, CD5." (PMID 41960458, 2026). "For B-cell lymphomas, emphasis is placed on the use of B-cell markers (CD19 and CD20) and other critical antigens (CD5, CD10, and CD38) for classification." (PMID 40075660, 2025). "No variations in CD79b expression were observed considering expression levels of other B-cell lymphoma markers, such as CD10, CD5, CD19, and CD20." (PMID 39682155, 2024). "Bone marrow tissue biopsy was performed, showing CD20 (+), CD79a (+), CD3 (–), CD5 (-), CyclinD1 (-), Bcl-2 (+), Bcl-6 (-), CD10 (-), MUM-1 (+), and Ki67 (+>50%), and a pathological diagnosis of high-grade B-cell non-Hodgkin lymphoma was made." (PMID 36032118, 2022).
B-cell lymphoma (continued). "In the present study, we comprehensively evaluated the expression of T-cell markers (CD2, CD3, CD4, CD5, CD7, and CD8) in 501 B-cell lymphomas, including 225 DLBCLs, by flow cytometry and subsequent immunohistochemistry." (PMID 28380441, 2017). "However, other B-cell lymphomas may sometimes express CD5 aberrantly." (PMID 28380441, 2017). "As a B cell lymphoma, MCL is characterized by the presence of characteristic B cell expression patterns with high (> 90%) expression of CD5, CD19, CD20, CD21, CD22, CD43, CD79a, sIg, and cIg, and low (< 10%) expression of CD10 and CD23." (PMID 27119356, 2016). "The most represented aberrancies in B-cell lymphoma were MHCII- (9/17, 53%), CD3+/CD21+ (7/17, 41%), CD34+ (4/17, 24%), CD79a- (4/17, 24%), while CD3+/CD21+ (5/8, 63%), CD4-/CD8- (4/8, 50%), CD45- (4/8, 50%), CD5- (4/8, 50%) were expressed in T-cell lymphoma." (PMID 37908841, 2023). "Looking at the clinical data of dogs presenting with CD5+ B-cell lymphoma, the age at diagnosis appears higher than in dogs without this phenotypic aberrancy (median 12.5 and 8 years, respectively)." (PMID 35448684, 2022). "Of note, even in the absence of an overt leukemic picture, indolent CD5-positive B-cell lymphomas frequently involve the BM and/or PB to a degree that allows diagnostic sampling." (PMID 34898558, 2021). "In addition, MCL, which is derived from B-cell lymphoma, is a subtype of NHL; the immune phenotype is a mature B-cell phenotype, and excessive CD20 and CD5 antigens are expressed on the surface of MCL cells." (PMID 29682183, 2018). "The tumors were CD5+, CD19+ B cell lymphomas that showed robust CSR capacity upon stimulation." (PMID 21269511, 2011). "Moreover, the cells were found to be positive for CD20, BCL-2, BCL-6 and IRF-4 (Mum-1) and be negative for CD10 and CD5 by Immunofluorescence, which was similar to the immunophenotypic profiles of the majority of HBsAg-positive B-cell NHL patients." (PMID 31120924, 2019). "Despite displaying non-specific immunohistochemistry markers such as CD3, CD5, CD10, Bcl-2, CD19, CD20, CD21, and CD23, a definitive diagnosis can only be made after ruling out other small B-cell lymphomas." (PMID 39188441, 2024). "Bone marrow biopsy and aspirate showed a scant low-grade B-cell lymphoma that coexpressed the B cell markers CD19 and CD20, as well as the CLL markers CD5 and CD23, but lacked CD10 or CD38." (PMID 29740389, 2018). "Positive expression of CD11a, CD79α, CD45, CD45RA, and MHCII and no expression of CD3, CD4, CD5, CD8, CD11d, CD14, CD21, CD34, and CD56 classifies it as a B-cell lymphoma." (PMID 27639374, 2016). "Immunohistochemical stain revealed that tumor cells were diffusely positive for CD20, CD79a, bcl-2, and negative for CD3, CD5, CD10, cyclin D1 and bcl-6, which excludes the possibility of low grade B-cell lymphoma other than EMZL." (PMID 26111022, 2015). "A repeat AC paracentesis was performed for cytological analysis, which revealed monoclonal B-cell lymphoma population positive for CD20, CD5, cyclin D1, and SOX11 but negative for CD10, CD3, and S100." (PMID 26450638, 2015). "The main CD10-positive/CD5-negative entities that can be characterized by FC include follicular lymphoma, Burkitt lymphoma, and a subset of diffuse large B-cell lymphoma, NOS and high-grade B-cell lymphomas." (PMID 40075660, 2025). "Therefore, the expression of T-cell markers other than CD5, such as CD2, CD4, CD7, and CD8, has not been broadly investigated in a large case series of B-cell lymphomas." (PMID 28380441, 2017).
diffuse large B-cell lymphoma (51 papers, 2010 to 2026). "A liver biopsy was diagnostic of CD5+ CD20+ diffuse large b-cell lymphoma of the liver." (PMID 31123642, 2019). "CD5-positive diffuse large B-cell lymphoma (DLBCL) is a rare variant, representing approximately 5%-10% of all DLBCL cases and is associated with advanced age, extranodal involvement, and poorer prognosis." (PMID 41969301, 2026). "Despite its low frequency in all variants of diffuse large B-cell lymphoma (DLBCL), CD5(+) DLBCL is the most well-studied CD5+ B-cell neoplasm with poorer outcomes compared to CD5- DLBCL." (PMID 39410047, 2024). "TRPM4 mRNA upregulation (together with the downregulation of other genes) in CD5+ subtypes of diffuse large B-cell lymphoma (DLBCL) patients was associated with a poorer prognosis compared with CD5− patients." (PMID 35056097, 2021). "Fourteen years after initial diagnosis, she developed CNS symptoms with cerebellar lesions; resection revealed transformed diffuse large B-cell lymphoma (DLBCL) of germinal center origin (CD5+, CD10+, BCL2, BCL6, MYC+, Ki-67 ~70%)." (PMID 41146768, 2025). "Combined with immunohistochemistry, non-Hodgkin lymphoma was considered as “primary CD5+ diffuse large B-cell lymphoma” and “leg type” with focal necrosis." (PMID 41341395, 2025). "Ultrasound examination revealed hypoechoic myometrium (hematoma considered), and ultrasound-guided puncture biopsy confirmed “primary CD5+ diffuse large B-cell lymphoma (leg type)”." (PMID 41341395, 2025). "Molecular pathological analysis revealed that this case was primary CD5+ diffuse large B-cell lymphoma “leg type” with focal necrosis." (PMID 41341395, 2025). "Based on the morphology and immune profile, a diagnosis of diffuse large B-cell lymphoma, CD5-positive, with centroblasts morphology." (PMID 36827036, 2023). "In patients with CD5+ subtypes of diffuse large B-cell lymphoma (DLBCL), the upregulation of TRPM4 mRNA was related to a poorer prognosis compared to CD5− patients." (PMID 36844925, 2022). "CD5-positive diffuse large B-cell lymphoma (CD5+ DLBCL) is a rare subtype of DLBCL with invasive clinical features and poor prognosis." (PMID 34804942, 2021). "Bone marrow biopsy and subsequent histopathological and immunohistochemical analyses led to a definite diagnosis of CD5-positive diffuse large B-cell lymphoma (DLBCL)." (PMID 32156266, 2020). "Patients diagnosed as diffuse large B cell lymphoma (DLBCL) with CD5 positive normally have a worse outcome and poorly respond to the regulatory treatment strategy." (PMID 31775867, 2019). "We report the first well-documented CD5+ primary cutaneous diffuse large B-cell lymphoma-leg type (PCDLBCL-LT)." (PMID 30792929, 2019). "Biopsy of the neck lymph nodes confirmed the diagnosis of CD5+ diffuse large B-cell lymphoma (lower right)." (PMID 28183687, 2018). "CD5-positive diffuse large B-cell lymphoma (DLBCL) and intravascular large B-cell lymphoma (IVL) are recognized as rare subsets of large B-cell lymphoma with poor prognosis." (PMID 30041681, 2018). "CD5 has also been found to be expressed, albeit rarely, in de novo diffuse large B-cell lymphoma (DLBCL)." (PMID 25760242, 2015). "CD5 is a pan-T-cell surface marker and is rarely expressed in diffuse large B-cell lymphoma (DLBCL)." (PMID 25760242, 2015). "CD5 mediated tumor survival through JAK-STAT signaling pathways in diffuse large B-cell lymphoma." (PMID 38767825, 2024). "Aberrant expression of CD5 has been reported in 5–10% of diffuse large B-cell lymphomas (DLBCLs)." (PMID 31644584, 2019). "However, the rare situation of a leukemic phase of CD5+ diffuse large B-cell lymphoma sometimes mimics acute lymphoid leukemia and requires careful differentiation." (PMID 28183687, 2018). "Only very rare cases of diffuse large B-cell lymphoma with aberrant expression of non-CD5 T-cell markers such as CD2 and CD7 have been reported, none of which to our knowledge have CD7 expression while arising in a background of a CD7 negative follicular lymphoma." (PMID 27774324, 2016).
diffuse large B-cell lymphoma (continued). "CD5-positive diffuse large B-cell lymphoma (CD5(+) DLBCL) is a rare immunophenotypic subtype of DLBCL, typically characterized by high aggressiveness, rapid disease progression, and poor prognosis." (PMID 41991306, 2026). "CD5+ diffuse large B-cell lymphoma (DLBCL) is a rare subtype with aggressive clinical behavior characterized by a high frequency of MYD88L265P mutations and CD79B mutations associated with persistent activation of the B-cell receptor (BCR) signaling pathway." (PMID 41341395, 2025). "CD5-positive diffuse large B-cell lymphoma (CD5+ DLBCL) showed poor prognosis in the rituximab era, with limited research on its genetic characteristics and cell of origin (COO)." (PMID 36081566, 2022). "The expression of CD5 in diffuse large B-cell lymphoma (DLBCL) can be observed in Richter transformation of CLL but can also be found in de novo DLBCLs." (PMID 31644584, 2019). "Approximately 10% of the diffuse large B-cell lymphomas (DLBCLs) express CD5, and such cases comprise an immunohistochemical subgroup of DLBCL, according to the 2008 WHO classification." (PMID 28380441, 2017). "In diffuse large B cell lymphoma, SH3TC2 was identified as a signature gene of the poor prognostic CD5+ activated B-cell like (ABC) subtype." (PMID 32637351, 2020). "Pathological diagnosis of non-Hodgkin's lymphoma, subtype; diffused large B cell lymphoma (WHO 2008, CD5+, high value-added activity) was made." (PMID 29610634, 2017). "Likewise, CD5+ MZL has been shown to have higher rates of transformation to diffuse large B-cell lymphoma and have lower response rates (30% vs. 77%), PFS (25% vs. 45% at 3 years), and OS (44% vs. 77%) to rituximab compared to their CD5- counterparts." (PMID 39410047, 2024). "Immunohistochemical analysis showed positive immunoreactivity for CD20, but negative for CD3 and CD5, the pathological diagnosis of diffuse large B-cell lymphoma (DLBCL) was obtained." (PMID 26726014, 2016). "In this study, cyclin D2 was found to be overexpressed in 98% of de novo CD5-positive diffuse large B-cell lymphomas (DLBCLs) (50/51) and in 28% of CD5-negative DLBCLs (14/51)." (PMID 23675804, 2013). "Diffuse large B-cell lymphomas(DLBCL) are the most commonly encountered type in the gastrointestinal tract.Most of the DLBCL are CD5 negative." (PMID 31814435, 2019). "A CT-guided adrenal biopsy showed diffuse large B-cell lymphoma (DLBCL) with expression of CD20, CD10, BCL-6, and MUM-1, but without CD5 expression." (PMID 40969788, 2025). "Intriguingly, within diffuse large B-cell lymphoma (DLBCL), MNDA expression is more prevalent in the non-germinal center B-cell (non-GCB) subtype and the BCL2/MYC double-expression group, displaying a correlation with CD5 expression—a finding that merits further exploration." (PMID 40386782, 2025).
autoimmune disease (31 papers, 2010 to 2025). A disorder resulting from loss of function or tissue destruction of an organ or multiple organs, arising from humoral or cellular immune responses of the individual to their own tissue constituents. "The loci identified included SNPs in immune response genes linked to autoimmune diseases including Crohn’s disease, ulcerative colitis, multiple sclerosis, and T1D (CD5, CCL2, IL23R, CD86, HLA, C11ORF30-LRRC32, CLEC16A)." (PMID 29454391, 2018). "CD5 levels are modified by the autoimmune disease associated H-2g7 haplotype." (PMID 39471840, 2024). "Because of the NAb ability to bind self-antigens, they may serve as templates for some of the high-affinity autoantibodies that emerge in patients with autoimmune disease, particularly those associated with a significant expansion of CD5 + B cells." (PMID 33178202, 2020). "CD5+/CD3 + cells have furthermore been reported to represent B-1a cells related to autoimmune disease." (PMID 40840919, 2025). "IL-17A, TCR+ γδ T cells, and CD5+ В1 cells play a crucial role in preventing pneumococcal infection, but can also contribute to autoimmune diseases." (PMID 38840926, 2024). "In this study, we aimed to understand the relationship between the constitutively expressed T cell co-inhibitory molecules BTLA and CD5, and an induced co-inhibitor, PD-1, in the steady state and under conditions that promote multi-organ autoimmune disease." (PMID 39471840, 2024). "In many autoimmune disorders, CD5+ B cells are reported to expand and to be a major source of natural polyreactive and autoreactive autoantibodies." (PMID 37373490, 2023). "CD5+ B cells primarily produce IgM-type natural antibodies and play an essential part in tissue homeostasis, autoimmune diseases, anti-infection, and anti-atherosclerosis." (PMID 38012211, 2023). "A relevant B cell population in autoimmune diseases is B1a cells (CD5+), responsible for the production of natural antibodies." (PMID 35211864, 2022). "Further, human CD5-expressing B cells were reported to produce autoreactive IgM antibodies and to be increased in patients with autoimmune diseases." (PMID 30941130, 2019). "CD5 expression on B cells is a common feature of both RA and CLL, CD5 expression correlates with RAG activity in B cells of people with autoimmune disease, and RAG is expressed in B cells in the RA synovium." (PMID 24988487, 2014). "The CD5 antigen-like molecule seems to play a critical role in autoimmune disorders, mediating B lymphocytes, whereas the apoA-I improves vascular complications in a mouse model of SSc." (PMID 20730046, 2010). "Despite this, increased CD5 on newly generated T cells was not sufficient for preventing autoimmune disease following transfer to immune-deficient mice." (PMID 39471840, 2024). "Finally, we examined cis-pQTLs of the HLA-pGenes identified from the flagship pQTL study, and found that the cis-pQTLs of five HLA-pGenes—CD5, CD6, IL7R, SLAMF8, and TNFSF11—are themselves associated with autoimmune diseases with HLA risk." (PMID 39085222, 2024). "As a pan T cell marker, CD5 is highly expressed in a variety of autoimmune diseases, and this MR study provides new evidence that elevated levels of circulating CD5 may directly promote the development of ASD." (PMID 38742104, 2024). "Unfortunately, little is known about the functional potential of CD5+ B cells and the role they may play in the pathophysiologic mechanisms of human autoimmune diseases." (PMID 38179278, 2023). "This included a CD5 locus that was significantly associated with IgD+ CD5++ proportion in B cells, which may be important as recent studies have reported the relevance of IgD+ CD5++ B cells in T1D and other autoimmune diseases such as Graves’ disease." (PMID 35638288, 2022). "The number of CD5+ B cells is expanded in such autoimmune diseases as RA and SS33,35." (PMID 31974463, 2020).